ATF4 (activating transcription factor 4)
Diseases named in the same sentence as ATF4 in open-access papers (continued):
Sharing a sentence is not in itself a finding about the gene and the disease.
glioblastoma (continued). "Furthermore, luteolin-induced ER stress response (p-PERK/p-eIF2α/ATF4/CHOP/caspase-12 pathway) was reversed in glioblastoma cells by treatment with the antioxidant N-acetylcysteine." (PMID 31316722, 2019). "Since ATF4 protein expression is known to be activated through phosphorylation of eIF2α, we examined eIF2α phosphorylation levels after Sunitinib treatment in a number of BTICs and glioblastoma cell lines." (PMID 30719230, 2019). "In our experiments, the treatment of A-172 glioblastoma cells for 24 and 48 h with sorafenib led to an increase in the expression of mRNA of the spliced form of the XBP1s transcription factor and did not change the expression of two other markers of ER-stress, ATF-4 and ATF-6." (PMID 36768736, 2023). "Furthermore, we found that decreased ATF4 and xCT expression in RSL3-treated cells could be prevented by NF-κB pathway inhibition, and NF-κB pathway activation in GPX4-depleted glioblastoma cells reduced ATF4 and xCT expression." (PMID 34987700, 2021). "Therefore, NF-κB pathway activation was essential for glioblastoma cell ferroptosis and might mediate ATF4 and xCT expression." (PMID 34987700, 2021). "Our previous study determined that boric acid triggered ER stress by regulating GRP78, ATF4 and CHOP in U251 glioblastoma cells." (PMID 40682482, 2025). "ATF4, the downstream transcriptional factor of PERK, promotes fructolysis under glucose-deprived conditions in glioblastoma, supporting cell proliferation." (PMID 41193471, 2025). "We therefore applied the combination of ONC201, TMZ and RT to SNB19, T98G, U138, and U251 glioblastoma cells and performed Western blot analysis of the expression of PARP, ATF4, LC3B and ClpX." (PMID 40145650, 2025). "It has been also described that NF-κB activation in glioblastoma cells by RSL3 treatment leads to an increase of lipid ROS and a reduction of anti-ferroptosis proteins such as GPX4, ATF4, and SLC7A11." (PMID 38539832, 2024). "Furthermore, ATF4 overexpression alone proved sufficient to induce CHAC1 expression in GBM cells, resulting in the generation of oxidized lipids and subsequent cell death in glioblastoma cells." (PMID 38291540, 2024). "In glioblastoma, PHGDH has been identified as a key target of ATF4 in endothelial cell (EC) metabolism." (PMID 38601083, 2024). "Recent studies have shown that the ATF4-CHOP axis induces senescence through G2/M phase arrest and apoptosis by activating the key target P21 in glioblastoma cells." (PMID 38169592, 2024). "Loperamide treatment of glioblastoma (GBM) promotes the UPR, and downstream ATF4 mediates the activation of the ER-phagy receptors FAM134B and TEX264 to promote ER degradation." (PMID 37794028, 2023). "Upon transfecting miR-320a mimic in cells with low endogenous miR-320a, such as glioblastoma T98G cells, HeLa cells and mouse embryonic fibroblast (MEF) cells, Tg-induced ATF4 activation was further elevated (compare lane 3s to lane 4s)." (PMID 34914716, 2021). "ATF4 and xCT protein levels remained the same in GPX4-depleted cells, but their expression was downregulated in RSL3-treated glioblastoma cells." (PMID 34987700, 2021). "We found that RSL3 led to an increase in lipid ROS concentration and downregulation of ferroptosis-related proteins such as GPX4, ATF4, and SLC7A11 (xCT) in glioblastoma cells." (PMID 34987700, 2021). "RSL3-induced ferroptosis in glioblastoma cells was characterized by an increase in lipid ROS and a decrease in GPX4, ATF4, and xCT expression." (PMID 34987700, 2021). "Moreover, we found that increased ATF4 and xCT expression correlates with GPX4 knockdown, while ATF4 and xCT are considered to play a protective role against ferroptosis in glioblastoma cells." (PMID 34987700, 2021). "Similarly, the motifs CGR (breast invasive carcinoma), CACAAR (glioblastoma multiforme), ATGWTG (lung squamous cell carcinoma), CGWCCGAA (prostate adenocarcinoma) show exclusive affinity for YY2, RUNX1, ATF4 and ZBTB7B, respectively." (PMID 32015379, 2020).
glioblastoma (continued). "Moreover, in a window of opportunity study, oral ONC201 induced the expression of ATF4 and DR5 in recurrent glioblastoma tissues, suggesting that ONC201 has biological activity in these tumors." (PMID 33194693, 2020). "In consistent with the previous study, KPNB1 inhibition-induced upregulation of Noxa and Puma and apoptosis in glioblastoma cells depends on ATF4 but not CHOP." (PMID 29520102, 2018). "TMZ markedly induces system xc- expression via the activation of activating transcription factor 4 (ATF4) and Nrf2 pathway in glioblastoma multiforme (GBM) cells." (PMID 30925886, 2019).
lung carcinoma (51 papers, 2016 to 2026). "Increased levels of HO-1 in lung cancer was associated with low survival of patients with lung carcinoma and HO-1 was defined as a mediator of ATF-4-dependent anoikis resistance and metastases." (PMID 26993595, 2016). "In colon and lung cancer, activation of p‐eIF2α and ATF4 signaling increases resistance to chemotherapy." (PMID 40873119, 2025). "More specifically, ATF4 overexpression leads to multidrug resistance, while ATF4 knockout reduces glutathione synthesis and increases chemotherapy sensitivity in lung cancer." (PMID 40873119, 2025). "For example, a study showed that ATF4 regulated the Wnt/β-catenin signaling pathway to promote the proliferation and invasion of lung cancer cells." (PMID 39090107, 2024). "EC therapy activates the PERK–eIF2α–ATF4 signaling pathway to increase ER stress, thereby promoting ferroptosis in lung cancer cells and inhibiting the occurrence and development of lung cancer." (PMID 39480832, 2024). "In conclusion, we found that EC treatment increases ER stress by activating the PERK–eIF2α–ATF4 signaling pathway, thereby promoting iron-related death in lung cancer cells and alleviating lung cancer progression." (PMID 39480832, 2024). "In summary, this study aims to explore in depth the role of EC in the PERK/eIF2α/ATF4 signaling pathway, which regulates the effect of ER stress on ferroptosis in lung cancer cells." (PMID 39480832, 2024). "RPL41 promotes ATF4 translocation to the cytoplasm, increases the ATF4 phosphorylation, thus accelerating ATF4 degradation and sensitizing lung cancer and retinoblastoma cells to chemotherapeutic drugs." (PMID 39261452, 2024). "Kristen rat sarcoma (KRAS), the most common mutated oncogene in human cancers, cooperates with NRF2 to upregulate ATF4 expression during nutrient stress, thereby modulating the amino acid uptake and asparagine biosynthesis in lung cancer." (PMID 39261452, 2024). "According to previous studies, higher nuclear ATF4 expression was detected in lung cancer cells compared to cytoplasmic ATF4 expression." (PMID 36900220, 2023). "Compared with normal cells, PERK phosphorylation, eIF2α phosphorylation, and ATF-4 levels were higher in A549 lung cancer cells." (PMID 37215572, 2023). "Lung cancer cells overexpress ATF4 and localize it primarily to the nucleus, which leads to an increase in lung cancer cell proliferation and invasion." (PMID 36900220, 2023). "According to reports, ATF4 is crucial in ER-negative breast malignancies, lung cancer, colorectal cancer, prostate cancer, and other types of cancer." (PMID 36900220, 2023). "ATF4 is involved in promoting colony formation, progression, and metastasis in hepatocellular and lung carcinomas." (PMID 35484984, 2022). "The expression levels of GRP78, p‐PERK, IRE1, ATF6, ATF4 and p‐eIF2α were increased in all three human lung cancer cells in a dose‐dependent manner." (PMID 34854221, 2022). "So, it is of great importance to discover the involvement of the ATF4-AKT-mTOR signaling pathway in the anti-tumor activity of fluoxetine in lung cancer cells." (PMID 35620287, 2022). "A similar result was also reported in lung cancer that showed that 20(S)-GRh2 triggers ER stress-related ATF4/DDIT3-induced apoptosis." (PMID 36431966, 2022). "It has been previously reported that ATF4 was overexpressed and primarily localized in the nucleus in lung cancer cells." (PMID 34976799, 2021). "Western blotting analysis shows that ATF4 was highly expressed in lung cancer cells compared to HBE cells (p < 0.05)." (PMID 33628101, 2021). "When ATF4 was overexpressed, colony formation increased and invasive cancer cells were more numerous, indicating the important role of ATF4 in regulating lung cancer cell growth and invasion." (PMID 33628101, 2021). "In summary, the present study firstly demonstrated that AD induced Noxa-dependent apoptosis by transactivating ATF4 in human lung cancer cells." (PMID 33995110, 2021).
lung carcinoma (continued). "In a summary, in this study we found that ATF4 is mainly located in the nucleus of lung cancer cells including A549, LK2 and H1299." (PMID 33628101, 2021). "In the present study, we found that AD exhibits a broad-spectrum inhibition of proliferation in lung cancer cells, and firstly demonstrated that AD activated the ATF4/Noxa axis to induce apoptosis of human lung adenocarcinoma cells." (PMID 33995110, 2021). "A previous study also demonstrated that ASNS was recognized by ATF4 and contributes to protein biosynthesis in lung cancer." (PMID 34976799, 2021). "In this study, we demonstrated that AD exhibits a broad-spectrum proliferation inhibitory effect in lung cancer cells, and firstly reported that AD induced lung adenocarcinoma cell apoptosis via activating ATF4/Noxa axis." (PMID 33995110, 2021). "We detected cytoplasmic and nuclear ATF4 expression in lung cancer A549, H1299, and LK2 cells, and the total expression of ATF4 was higher than that in HBE cells (p < 0.05)." (PMID 33628101, 2021). "LicA increases the expression levels of ERS related proteins, such as p‐EIF2 α and ATF4, to inhibit the proliferation of lung cancer cells." (PMID 33650320, 2021). "We next verified that the AHR activator omeprazole induced expression of ASNS and ATF4 in three different lung cancer cell lines, H1975, A549, and H1299." (PMID 33214553, 2020). "Previously, oncogenic KRAS was described as regulator of ASNS induction by ATF4 in lung cancer models." (PMID 33214553, 2020). "The protein levels of PDL1, IRF1, IRF7, STAT1, STAT2, IFNAR1, eIF2α, and ATF4 in the normal and tumor tissues of 27 subjects with lung cancer were determined by Western blot." (PMID 30305853, 2018). "To further investigate the role of ATF4 in lung cancer cell viability following fucoidan treatment, we performed a crystal violet staining assay to examine cell viability and proliferation." (PMID 28332554, 2017). "We firstly examined the expressions of ER stress-related proteins p-EIF2α and ATF4 in LicA-treated lung cancer cells." (PMID 28805696, 2017). "Additionally, natural compounds like baicalin, solasodine, and ginsenoside Rh2 can also regulate ferroptosis in lung cancer cells by targeting key factors such as Nrf2, ATF4, HSP90, and IRF1." (PMID 41242017, 2025). "Through flow cytometry analyses, either PERK or ATF4 knockdown could significantly rescue apoptosis triggered by TRAF3IP3 overexpression in lung cancer cells." (PMID 40068093, 2025). "Finally, we revealed that EC therapy activates the PERK/eIF2α/ATF4 signaling pathway and promotes ER stress, thereby inducing ferroptosis in lung cancer cells and inhibiting the occurrence and development of lung cancer." (PMID 39480832, 2024). "ATF4 could activate the expression of genes involved in serine biosynthesis in response to serine starvation in lung cancer cells." (PMID 38601083, 2024). "Additionally, comprehensive metabolomic profiling of human lung cancer cells has shown that NRF2 also controls the serine biosynthesis metabolic program via activating transcription factor 4 (ATF4) and phosphoglycerate dehydrogenase activation." (PMID 35326187, 2022). "Whether these molecular links are involved in the function of ATF4 in lung cancer cells needs to be further investigated." (PMID 33628101, 2021). "ATF4 may promote the growth and invasion of lung cancer cells partly by promoting the activation of canonical Wnt pathway." (PMID 33628101, 2021).
lung carcinoma (continued). "In our current study, we demonstrate that fucoidan (i) promotes apoptosis of lung cancer cells, (ii) reduces lung tumorigenesis, (iii) induces ATF4 and CHOP protein expression in an LLC1-xenograft mice model via continuous oral feeding of fucoidan, and (iv) induces ROS-mediated ER stress via TLR4." (PMID 28332554, 2017). "Together, these results indicate that ATF4 may play a fucoidan-mediated cell death molecule that is involved in ER stress in lung cancer." (PMID 28332554, 2017). "Furthermore, an additional study revealed that fluoxetine hinders lung cancer progression through activation of the ATF4-AKT-mTOR signaling pathway, inducing cell cycle arrest and autophagy to impede cancer cell proliferation without affecting normal lung epithelial cell proliferation." (PMID 40110200, 2025). "Therefore, exploring the PERK/eIF2α/ATF4 axis may contribute to the development of new lung cancer diagnosis and treatment strategies by influencing ER stress to regulate ferroptosis in cancer cells." (PMID 39480832, 2024). "Notably, the authors discovered that the activation of AhR by omeprazole drove the suppression of lung cancer cells’ growth via an AhR-dependent induction of the expression of activating transcription factor 4 (ATF4) and upregulation of asparagine synthetase (ASNS)." (PMID 37106727, 2023). "In lung cancer, MTHFD2 is activated by ATF4 to maintain redox homeostasis and contributes to cancer progression by regulating AKT/GSK-3β/β-catenin signaling." (PMID 40918462, 2025). "We noted a significant association of SSP genes as well as SHMT2 and MTHFD2 with the expression of the asparagine synthase (ASNS), an activating transcription factor 4 (ATF4) regulated marker for amino acid and glucose deprivation in both lung cancer subtypes." (PMID 38515202, 2024). "It suppresses MMP-24 and upregulates activating transcription factor 4 (ATF4) and asparagine synthetase (ASNS), an enzyme controls the motility of lung cancer cells by endowing stability to the β-catenin complex and modifying mitochondrial response." (PMID 37241719, 2023). "Our results showed that fluoxetine triggered the ATF4-AKT-mTOR signaling pathway to induce cell cycle arrest and autophagy restraining cancer cells’ growth in lung cancer." (PMID 35620287, 2022). "Here, we investigated ATF4 expression in human bronchial epithelial HBE cells and lung cancer cells." (PMID 33628101, 2021). "Specifically, fucoidan increases the intracellular reactive oxygen species (ROS) that are responsible for the increases in ATF4 and CHOP protein expression and activates UPP to induce lung cancer cell death." (PMID 31041568, 2019). "Fucoidan increases intracellular reactive oxygen species (ROS), which are responsible for the increases in ATF4 and CHOP in lung cancer cells." (PMID 31041568, 2019). "Specifically, fucoidan increases intracellular reactive oxygen species (ROS), which increase ATF4 and CHOP in lung cancer cells." (PMID 28332554, 2017). "Here we also found that fucoidan activation of TLR4 and TLR4-mediated ROS-induced ER stress (PERK-eIF2α-ATF4-CHOP pathway), which involved in fucoidan-induced apoptosis (activation of caspase 3 and PARP) of lung cancer cells." (PMID 28332554, 2017). "Here we found that fucoidan induces CHOP expression in lung cancer cells; and the PERK-eIF2α-ATF4-CHOP signaling pathway is one of major pathways in ER stress-mediated apoptosis." (PMID 28332554, 2017). "In conclusion, these findings demonstrated that NUPR1 knockdown inhibits angiogenesis in A549 and H1299 cells through IRE1/XBP1 and PERK/eIF2α/ATF4 signaling pathways, indicating that NUPR1 could represent a novel lung cancer therapeutic target." (PMID 37854285, 2023). "At the same time, the β‐elemene upregulates the expression levels of ER‐related proteins, such as ATF6, PERK, IREα, ATF4, and CHOP, and downregulates the expression of Bcl‐2, which inhibits lung cancer growth and cell viability in a dose‐dependent and time‐dependent manner." (PMID 33650320, 2021).
lung carcinoma (continued). "The significant correlations among eIF2α, ATF4, IRF1, and PDL1 in lung cancer may result from ER stress-induced UPR/ISR and the PD1/PDL1 reverse signaling." (PMID 30305853, 2018). "However, in lung cancer cells, the SIRT1/2-specific inhibitor salermide upregulates pro-survival autophagy via HSPA5 acetylation and subsequent activation of activating transcription factor 4 (ATF4) and DNA damage inducible transcript 4 (DDIT4) to inhibit the mTOR signaling pathway." (PMID 36646695, 2023). "However, the canonical PERK-eIF2α-ATF4 did not account for the observed activation of ATF4 in lung cancer cells." (PMID 31020572, 2019). "The ATF4 modulation exerted by oncogenic KRAS is required for apoptosis suppression via control of asparaginase biosynthesis: inhibition of AKT suppresses asparaginase expression and, combined with low extracellular asparagine, decreased the growth of KRAS-mutant lung cancers." (PMID 30060526, 2018). "The different correlation profiles of IRF1, eIF2α, ATF4, and PDL1 protein expressions in the normal and tumor tissues of lung cancer, especially adenocarcinoma, may be helpful in selecting conditions for combining ICI and inhibitors against IDO1 or modulators of ER stress." (PMID 30305853, 2018). "However, whether PSAT1 contributes to the molecular regulation of Wnt/β-catenin signaling by ATF4 in lung cancer cells is not clear." (PMID 33628101, 2021).